INS (insulin)
Diseases named in the same sentence as INS in open-access papers (continued):
Sharing a sentence is not in itself a finding about the gene and the disease.
type 1 diabetes (continued). "The patient was a 41-year-old woman (height, 156 cm; weight, 49 kg) who had been diagnosed with type 1 diabetes at the age of 9 years and had been receiving insulin therapy long-term." (PMID 40951123, 2025). "Type 1 diabetes (T1D) is described by the destruction of the pancreatic β-cell within the islets of Langerhans, resulting in insulin depletion and hyperglycemia." (PMID 40860014, 2025). "Type 1 diabetes (T1D) is a chronic autoimmune disorder characterized by the destruction of insulin-producing β-cells in the pancreas, resulting in absolute insulin deficiency." (PMID 40077058, 2025). "Type 1 diabetes (T1D) arises from T cell-mediated destruction of insulin-secreting pancreatic β cells." (PMID 40684438, 2025). "Type-I diabetes patients constituted 50% of the sample, primarily using syringes for insulin (41.0%)." (PMID 40357213, 2025). "In 1922, a purified insulin extract was administered to a 14-year-old boy with type 1 diabetes (T1D) with spectacular success." (PMID 40574081, 2025). "Type I diabetes (T1D) is an autoimmune disease that destroys pancreatic β cells, resulting in an inability to produce insulin." (PMID 40182604, 2025). "Glycaemic therapy in type 1 diabetes (T1D) is focused on insulin, with the majority of studies investigating different insulin preparations, delivery devices and dosing accuracy methods." (PMID 40130476, 2025). "Another study performed in adults with type 1 diabetes showed that the DBLG1 system was superior to open-loop insulin delivery with respect to TIR3.9–10.0 and TAR>10.0 when the ‘Physical Activity’ mode was set 30 min before the start of activity." (PMID 39653802, 2025). "In the type 1 diabetes participants, the mean age was 37.4 ± 8.8 years (mean ± SD), with type 1 diabetes duration 22.9 ± 8.9 years, 60% male, BMI 26.3 ± 3.8 kg/m2, total daily insulin dose 0.6 (0.5, 0.7) units/kg/day (mean [IQR]) and HbA1c 7.5 ± 0.9%." (PMID 41285865, 2025). "Here we examined the impact of adding an intensive telehealth intervention to CGM use on glycemic control in children and adolescents with type 1 diabetes taking MDI insulin." (PMID 41049863, 2025). "The participants were adults with type 1 diabetes, diagnosed at least one year before the study, and receiving treatment via continuous subcutaneous insulin infusion (CSII) or multiple daily insulin injections (MDI), were included." (PMID 40917291, 2025). "In a proof-of-concept study, ultrasound stimulation of subcutaneously implanted microencapsulated engineered cells stably expressing the sonogenetic circuit in a type 1 diabetic mouse model triggered sufficient insulin production to restore normoglycemia." (PMID 40114374, 2025). "We experienced a case that followed a similar course to fulminant type 1 diabetes and then presented the recovery of insulin secretory ability." (PMID 40406776, 2025). "Type 1 diabetes (T1D) is a chronic autoimmune disorder characterized by autoreactive CD8+ T cells that destroy insulin-producing pancreatic β-cells." (PMID 40607421, 2025). "The drug was initially evaluated as adjunct therapy to insulin in type 1 diabetes, where it demonstrated significant improvements in glycemic control." (PMID 41551500, 2025). "Comparison of hyper-/hypoglycemic experience between different lines of insulin treatment among patients with type 1 diabetes." (PMID 41250728, 2025). "Individuals living with type 1 diabetes (T1D) require multi-daily insulin administration and glucose monitoring to maintain health and reduce the risk of diabetes-associated complications." (PMID 41179840, 2025). "When life expectancy is only hours and patients are unconscious, insulin can be stopped in type 1 diabetes as well." (PMID 40863223, 2025). "Type 1 diabetes is typically an autoimmune condition characterized by the destruction of insulin-producing β-cells in the pancreas, resulting in an absolute deficiency of insulin." (PMID 41311837, 2025).
type 1 diabetes (continued). "A similar proportion of type 1 diabetes participants used multiple daily insulin injections and insulin pumps." (PMID 41285865, 2025). "Type I diabetes results from autoimmune attacks against the insulin-producing β-cells, leading to an inability to produce necessary insulin." (PMID 41383402, 2025). "Previous research by Kruszynska and Home also suggested that individuals with type 1 diabetes traditionally required high insulin doses (>1.0 units per kilogram of body weight per day) to achieve satisfactory diabetic control." (PMID 38954647, 2025). "Insulin-dependent diabetes was more prevalent in the conventional cohort (3.14% vs. 0.11%), while insulin-independent diabetes showed a similar prevalence (24.19% vs. 26.68%)." (PMID 41404107, 2025). "Autoimmunity has been extensively studied in the pathogenesis of type 1 diabetes, and insulin has been described as a major autoantigen, especially insulin B-chain peptide (B9-23)." (PMID 40821816, 2025). "This retrospective study (October 2020–October 2023) included glucometric data from type 1 diabetes patients collected from the Asturias Automatic Insulin Devices Registry." (PMID 40666106, 2025). "This study confirms that, after 12 months of routine clinical use, the use of commercially available automated insulin delivery (AID) systems significantly improves glycemic control in individuals with type 1 diabetes." (PMID 40666106, 2025). "Several studies have shown that consumption of CM by patients with type 1 diabetes can lead to a significant reduction in blood glucose levels, along with a decrease in exogenous insulin requirements by up to 30%." (PMID 41007307, 2025). "Type 1 diabetes usually has an autoimmune origin and results from the destruction of the insulin-secreting pancreatic β-cells." (PMID 40806520, 2025). "A search of the database identified 95 122 people with type 1 diabetes matching the inclusion criteria, including 17 260 using an insulin pump." (PMID 40390300, 2025). "This meta-analysis evaluated the impact of adding DPP-4 inhibitors to insulin therapy, focusing on glycemic control as assessed by HbA1c, insulin requirements, and the implications for patients with type 1 diabetes." (PMID 41026724, 2025). "Comparison of the level of last glycated hemoglobin between different lines of insulin treatment among patients with type 1 diabetes." (PMID 41250728, 2025). "For a proof-of-concept study, we implant microencapsulated engineered monoclonal human cells expressing insulin under the control of the ASPIRIN system in a mouse model of type 1 diabetes (T1D)." (PMID 40016240, 2025). "For this reason, sulfatide has been proposed as a putative target to counter beta cell stress and preserve residual insulin production in newly diagnosed type 1 diabetes." (PMID 39477880, 2025). "Peripheral serum insulin concentrations were three- to fourfold higher in participants with type 1 diabetes compared with control participants during both interventions." (PMID 40210728, 2025). "Type I diabetes was the most common (92%), and so insulin was the main treatment in the majority (94%)." (PMID 39607902, 2025). "Type 1 diabetes (T1D) is precipitated by the autoimmune destruction of the insulin-producing β cells in the pancreatic islets of Langerhans." (PMID 40014407, 2025). "Type 1 diabetes results from the autoimmune destruction of the insulin-producing beta cells in the pancreas, requiring exogenous insulin for survival." (PMID 40832419, 2025). "Investigations focusing on strategies for the safe implementation of SGLT2 inhibitors in type 1 diabetes, including personalised insulin dose adjustments and ketone monitoring protocols, are also warranted." (PMID 40629004, 2025). "In some cases, early supplementation of thiamine reduces the need for insulin management of type 1 diabetes." (PMID 41210025, 2025).
type 1 diabetes (continued). "For this reason, and to improve the general outcome of the therapy, non-insulin drugs are implemented as adjunct agents in patients with type 1 diabetes." (PMID 41373413, 2025). "Ketogenic and very low-carbohydrate diets are gaining attention in type 1 diabetes, an autoimmune disorder that destroys the insulin-producing beta cells, for their ability to improve glycemic control and reduce insulin requirements." (PMID 40959698, 2025). "A review of individualised treatment of a resident with type 1 diabetes often results in a need to simplify the insulin regime." (PMID 39500566, 2025). "The objective of this study is to describe the short-term change observed in CGM-related measures and relevant clinical variables in individuals with type 1 diabetes transitioning to Omnipod 5 insulin treatment within a real-world setting." (PMID 41473236, 2025). "We conducted a randomized controlled trial comparing a DSS for weekly insulin adjustments compared to a standalone app with a bolus calculator in adults with type 1 diabetes and suboptimal glycemic control." (PMID 41022835, 2025). "In a cluster randomized trial examining the efficacy of insulin pumps versus MDI for adults with type 1 diabetes, both groups underwent comparable training in flexible insulin treatment." (PMID 41146752, 2025). "The lack of a correlation between glucose levels and EAT is attributed to the fact that instantaneous glucose levels in individuals with type 1 diabetes can be easily affected by diet, exercise, and insulin dosage." (PMID 38879626, 2025). "Background/Objectives: Previous studies reported impairments in insulin secretion during different stages of type 1 diabetes (T1D), while data regarding insulin sensitivity and immunological changes are still controversial." (PMID 40004639, 2025). "The variability of MIDD is typified by the families exhibiting both insulin dependent (presenting in diabetic ketoacidosis) and non-insulin dependent diabetes across first-degree relatives." (PMID 39891580, 2025). "Limiting carbohydrate intake has a long-standing history, once serving as a treatment for type 1 diabetes (T1D) before the discovery of insulin." (PMID 39610878, 2024). "Type 1 diabetes is an autoimmune disorder in which insulin-secreting beta cells in the pancreas are destroyed by the immune system." (PMID 38674161, 2024). "Participants were more likely to attend DSME if they had a medium (OR 1.82 [95%CI 1.21–2.73]),or high (OR 2.04 [95%CI 1.30–3.21]) level of education, had type 1 diabetes (OR 2.46 [1.24–4.90]) and insulin treatment (OR 1.96 [95%CI 1.33–2.90])." (PMID 39264968, 2024). "We report that virtual initiation of insulin pumps is safe and effective in children and adolescents with type 1 diabetes." (PMID 38745900, 2024). "Sitagliptin showed an overall reduction in blood glucose concentrations in adults with type 1 diabetes on the AHCL system when used as an add-on therapy with insulin." (PMID 39271520, 2024). "There were 23 men (0.8% of total sample) treated with insulin alone and were therefore presumed to have type 1 diabetes." (PMID 38829475, 2024). "Rechenberg and colleagues found that adolescents with type 1 diabetes reported increased worry about managing their health, particularly regarding hypoglycemia and correct insulin dosing." (PMID 38289663, 2024). "Extended use of an open-source automated insulin delivery system in children and adults with type 1 diabetes: the 24-week continuation phase following the CREATE randomized controlled trial." (PMID 39196351, 2024). "In type 1 diabetes (T1D), impaired glucagon release in response to low blood glucose levels (e.g., after an insulin injection) can lead to severe hypoglycemia and even death." (PMID 38879678, 2024). "The glucagon response to insulin-induced hypoglycaemia is markedly impaired in nearly all people with type 1 diabetes within approximately 5 years of disease diagnosis." (PMID 38010533, 2024).
type 1 diabetes (continued). "Type 1 diabetes is brought on by the body’s immune system attacking the pancreatic cells that produce insulin and insulin treatment must last throughout one’s life." (PMID 38645750, 2024). "A low-fat diet has been shown in another trial to increase peripheral insulin sensitivity in patients with type 1 diabetes." (PMID 39768947, 2024). "The current goal of insulin therapy in type 1 diabetes is to reach >70% of time in the target glucose range while minimising the burden of hypoglycaemia, together with decreasing the risk of development of long-term diabetes-related complications." (PMID 39271520, 2024). "The retest for GAD antibodies was performed to exclude type 1 diabetes due to decreased insulin secretion ability." (PMID 39247010, 2024). "Previous studies have reported heterogeneity in the progression to clinical type 1 diabetes in children who develop either insulin- or glutamic acid decarboxylase-specific antibodies as their first autoantibodies." (PMID 38714671, 2024). "For patients with type 1 diabetes, who require life‐long insulin administration, stable GV control is the main goal for clinical practitioners." (PMID 39588847, 2024). "In summary, the use of a user-initiated insulin delivery intensification mode is safe in children, adolescents, adults, and older adults with type 1 diabetes using the Cambridge HCL algorithm." (PMID 36475908, 2024). "Yet, incorrect assumptions leading to underdiagnosis of type 1 diabetes in adults mean many develop DKA before starting insulin therapy." (PMID 38910151, 2024). "Type 1 diabetes is a T cell-mediated autoimmune disease with progressive destruction of insulin-producing beta cells in the pancreas." (PMID 37782353, 2024). "Type 1 diabetes (T1D) is a T-cell organ-specific autoimmune illness that develops when the beta cells secreting insulin in islets of Langerhans selectively malfunction leading to reduced insulin production." (PMID 39390211, 2024). "Adherence to basal insulin injections and the effects of missed basal insulin injections in adults with type 1 diabetes (T1D) were investigated using data from continuous glucose monitoring (CGM) and smart insulin pen devices in a real-world study." (PMID 35775735, 2024). "We have reported on a case of HNF1A MODY in a female young adult living in a sub-Saharan African setting, who was misdiagnosed as having type 1 diabetes, and treated with multiple insulin injections." (PMID 39420387, 2024). "Type 1 diabetes, an autoimmune condition, leads to the destruction of insulin-producing beta cells in the pancreas, resulting in insulin deficiency." (PMID 38399498, 2024). "Our data demonstrate that the crosstalk with CD4+/CD25− T cells during the initial phases of type 1 diabetes triggers changes in the tRF beta cell landscape that contributes to the demise of the insulin-secreting cells." (PMID 38967669, 2024). "This study tried to identify optimal nonpharmacological interventions to reduce HbA1c levels as a primary outcome, and daily insulin requirements as a secondary outcome, compared to usual care conditions in children and adolescents with type 1 diabetes." (PMID 38951907, 2024). "In recent years, various antigens have been used to target pancreatic cells in type I diabetes, antigens such as insulin protein, CUZD1, ZNT8, GLUT1, etc48,49." (PMID 38355744, 2024). "This case demonstrates a possible reduction in insulin requirements in a patient with type 1 diabetes during montelukast treatment, likely related to its anti-inflammatory effects on eosinophils." (PMID 39749265, 2024). "For instance, women with Type 1 diabetes (typically treated with exogenous insulin) are more likely to exhibit ovarian dysfunction, and those taking a higher daily dose of insulin have an increased chance of earlier menopause." (PMID 38131197, 2024).
type 1 diabetes (continued). "We present a rare case of insulin-induced amyloidosis or amyloidoma, which slowly developed at a satellite location distant from the insulin pump site and required surgical excision in a patient with type 1 diabetes." (PMID 39081432, 2024). "In patients with type 1 diabetes, GH secretion can become dysregulated as elevated glucose levels and reduced insulin impair normal feedback mechanisms." (PMID 39560873, 2024). "Type 1 diabetes (T1D) is a chronic disease characterized by the immune-mediated destruction of the pancreatic beta cells responsible for insulin production." (PMID 39456927, 2024). "Type 1 diabetes requires periodic insulin infusion, however, AI-powered CGM devices can calculate the insulin dosage required at a particular time period." (PMID 39238969, 2024). "Type 1 diabetes occurs when the body’s immune system unintentionally targets and kills the pancreatic cells that produce insulin." (PMID 39766863, 2024). "After the discovery of insulin in 1922, porcine insulin was used to treat type 1 diabetic patients for 60 years." (PMID 38786050, 2024). "A compelling body of evidence has emerged from cases of robust type-1 diabetes characterized by the sudden onset of insulin-dependent hyperglycemia and, in some instances, ketoacidosis, even in individuals without detectable autoantibodies." (PMID 38287388, 2024). "Carbohydrate counting (CC) is widely used by patients with type 1 diabetes to adjust prandial insulin bolus doses based on estimated carbohydrate content, contributing to better glycemic control and improved quality of life." (PMID 39064626, 2024). "Type 1 diabetes management during pregnancy is challenging due to metabolic changes and marked gestational variation in insulin sensitivity." (PMID 39390689, 2024). "Our team is also conducting research on autologous insulin-producing cell-based agents for type 1 diabetes and autologous MSC-based agents for stroke, and investigator-initiated clinical trials of combination products of MSCs and biomaterials are underway." (PMID 39408838, 2024). "Type 1 diabetes mellitus (T1D) is a chronic autoimmune disease characterized by the destruction of beta cells, leading to insulin deficency." (PMID 39218890, 2024). "Type 1 diabetes (T1D) is a chronic disease characterized by persistent autoimmune destruction of β cells, leading to lifelong dependence on exogenous insulin." (PMID 38212850, 2024). "In this study, the authors examine the T cell receptor (TCR) repertoire of insulin antigen-reactive T cells from peripheral blood from patients with type-1 diabetes as well as pancreata from deceased donors." (PMID 38871688, 2024). "Type 1 diabetes (T1D) is a chronic autoimmune condition wherein the body’s immune system erroneously attacks and destroys insulin-producing beta cells in the pancreas." (PMID 38337523, 2024). "Type 1 diabetes (T1D) is a chronic metabolic disorder that results from progressive autoimmune destruction of insulin-producing pancreatic beta cells in the islets of Langerhans." (PMID 38534794, 2024). "Cardiac adiponectin induced by long-term insulin treatment can significantly reduce MI/RI in type 1 diabetic mice." (PMID 38347951, 2024). "In summary, these studies provide insights into the potential of closed-loop systems and insulin pumps in enhancing glycemic control in insulin-dependent diabetes." (PMID 39238969, 2024). "The study was motivated by the fact that elevated Lp(a) levels decreased after insulin therapy in patients with type 1 diabetes (T1D)." (PMID 39210428, 2024). "Clinical studies on the treatment of type 1 diabetes with device-encapsulated pancreatic precursor cells derived from human embryonic stem cells found that insulin output was insufficient for clinical benefit." (PMID 38012450, 2024). "This trial was a significant milestone, as it improved his condition and was the basis for the discovery of insulin as the critical element in the disease pathology of Type I diabetes." (PMID 39691108, 2024).